ARPC4-TTLL3 (ARPC4-TTLL3 readthrough)
Gene: Protein-coding gene on chromosome 3 (9,793,082 to 9,835,401, forward strand). Ensembl gene ENSG00000250151.
Genetic constraint (gnomAD): Loss-of-function variants: 55 observed, 71.25 expected, observed/expected ratio (o/e) 0.77, 90% interval 0.62 to 0.97. The upper end of that interval is the gene's LOEUF score, 0.97, which puts it in group 4 of 6, group 1 being the genes least tolerant of losing a copy. Missense variants: 683 observed, 836.93 expected, observed/expected ratio (o/e) 0.82, 90% interval 0.77 to 0.87. Synonymous variants: 297 observed, 318.61 expected, observed/expected ratio (o/e) 0.93, 90% interval 0.85 to 1.03.